UBXN11 (UBX domain protein 11)
Description:
May be involved in the reorganization of actin cytoskeleton mediated by RND1, RND2 and RND3. Promotes RHOA activation mediated by GNA12 and GNA13 (By similarity).
Synonyms: SOC; UBXD5; PP2243; SOCI; COA-1
Tractability: Antibody: the Human Protein Atlas places it where antibodies can reach. PROTAC: ubiquitination databases record sites on it.
Gene: Protein-coding gene on chromosome 1 (26,281,328 to 26,318,363, reverse strand). Ensembl gene ENSG00000158062.
Subcellular location: Cytoplasm, cytoskeleton
Subcellular location (Human Protein Atlas): Basal body; Cytosol
Pathways (Reactome):
Signal Transduction: RND1 GTPase cycle; RND2 GTPase cycle; RND3 GTPase cycle
Gene Ontology:
Molecular function: protein binding; ubiquitin binding
Biological process: proteasome-mediated ubiquitin-dependent protein catabolic process
Cellular component: cytosol; cytoskeleton
Genetic constraint (gnomAD): Loss-of-function variants: 39 observed, 53.66 expected, observed/expected ratio (o/e) 0.73, 90% interval 0.56 to 0.95. The upper end of that interval is the gene's LOEUF score, 0.95, which puts it in group 4 of 6, group 1 being the genes least tolerant of losing a copy. Missense variants: 580 observed, 591.37 expected, observed/expected ratio (o/e) 0.98, 90% interval 0.92 to 1.05. Synonymous variants: 261 observed, 239.12 expected, observed/expected ratio (o/e) 1.09, 90% interval 0.99 to 1.21.
Homologues: Orthologues: chimpanzee UBXN11 (96% identical), macaque UBXN11 (91% identical), mouse Ubxn11 (75% identical), rat Ubxn11 (74% identical), dog UBXN11 (74% identical), guinea pig UBXN11 (68% identical), pig UBXN11 (61% identical), rabbit UBXN11 (61% identical), tropical clawed frog ubxn11 (35% identical), zebrafish ubxn11 (32% identical). Paralogues in human: NSFL1C (14% identical), UBXN2B (12% identical), UBXN2A (11% identical).
Diseases named in the same sentence as UBXN11 in open-access papers:
UBXN11 is named in the same sentence as 17 diseases in open-access papers, as found by Europe PMC text mining. Sharing a sentence is not in itself a finding about the gene and the disease. The quoted sentences say what the papers report.
systemic lupus erythematosus (3 papers, 2020 to 2025). An autoimmune multi-organ disease typically associated with vasculopathy and autoantibody production. "We found that cg00768487 (UBXN11) and cg03110787 (MLLT1) have been associated with papillary thyroid carcinoma, cg10806146 (SLC20A2) and cg15936066 (SLC20A2) with prostate cancer, cg15936066 (SLC20A2) with systemic lupus erythematosus, and cg07538190 (C8orf58) with psoriasis." (PMID 32493484, 2020). "Given their absence in controls and potential functional relevance, and the limited prior research on their roles in SLE, we propose MXRA8, NADK, POLR3GL, and UBXN11 as candidate genes for further investigation in the context of systemic lupus erythematosus." (PMID 40777011, 2025).
craniofacial microsomia (1 paper, 2025). "Additionally, genes like PDE4DIP, UBXN11, and AXIN1 are associated with hepatocellular carcinoma, and a de novo mutation in the SF3B2 gene relates to craniofacial microsomia." (PMID 40136557, 2025).
dilated cardiomyopathy (1 paper, 2020). Cardiomyopathy which is characterized by dilation and contractile dysfunction of the left and right ventricles. "An EWAS involving cardiac tissue samples has found differential methylation of a CpG in UBXN11 associated with dilated cardiomyopathy in adults." (PMID 32493484, 2020).
tumor (6 papers, 2019 to 2024). "Additional genes that had similar DNA and RNA frequency as DUSP5 and EI24 but no previous research on their potential role as a tumor suppressor were UBXN11, CAPN15, C6orf62, GPRIN1, KIAA2018, PCDHGA10, and PCGF1." (PMID 31484939, 2019). "However, it remains unknown whether the remaining members of the UBXD family, such as UBXN4, UBXN11, and UBXN2B, have effects on tumour formation and progression in vitro and in vivo." (PMID 38365777, 2024).
cancer (3 papers, 2020 to 2024). A tumor composed of atypical neoplastic, often pleomorphic cells that invade other tissues. "In the UBXN11 protein, cancer cells are weakly stained or negative in most cases, and only a small number of breast, prostate, and pancreatic cancer cases were moderately stained." (PMID 38365777, 2024).
UBXN11 also shares sentences with these, for which no sentence is quoted: infection (2 papers); ) virus infection (1); anaplastic thyroid carcinoma (1); breast carcinoma (1); hepatocellular carcinoma (1); mastitis (1); mental illness (1); Obesity (1); papillary thyroid carcinoma (1); Prader-Willi syndrome (1); prostate carcinoma (1); psoriasis (1).